SMAD3 (SMAD family member 3)
Diseases named in the same sentence as SMAD3 in open-access papers (continued):
Sharing a sentence is not in itself a finding about the gene and the disease.
diabetic nephropathy (56 papers, 2009 to 2025). "It is well documented that Smad3 is pathogenic since knockout of Smad3 gene inhibits fibrosis in obstructive nephropathy, diabetic nephropathy, hypertensive nephropathy, and drug-toxicity-related nephropathy." (PMID 25852569, 2015). "The inhibitory effect of CHYS on diabetic kidney disease was associated with inactivation of TGF-β/Smad3 signaling." (PMID 24646636, 2014). "Additionally, Smad3 signaling was found to modulate the inflammatory response, as Smad3 deficiency mitigated NF-κB signaling-dependent inflammation in diabetic nephropathy." (PMID 39135084, 2024). "Notably, three protein‐coding genes (Upk1b, Psca and Gdf15) and two lncRNAs (NONMMUG023520.2 and NONMMUG032975.2) were identified to be Smad3‐dependent and to be associated with the development of diabetic nephropathy." (PMID 33369170, 2021). "Interestingly, our previous study indicated that the activation of TGF-β1/Smad3 could be attributed to the loss of Smad7 signaling in diabetic nephropathy." (PMID 34775979, 2021). "Beyond enhancing NLRP3 expression through FcγRs/NF-κB signaling, CRP promotes diabetic nephropathy progression through Smad3-mediated activation of NLRP3 inflammasomes." (PMID 41377556, 2025). "Further investigations have shown that Sirt6 directly interacts with Smad3, where it deacetylates Smad3, thereby inhibiting its transcriptional activity and nuclear accumulation, offering protection against renal injury in diabetic kidney disease." (PMID 39911234, 2024). "The seldom reports of C3aR antagonist treatment in Type II diabetic rats ameliorating diabetic nephropathy hold discrepancies as to the observed effect being due to the suppression of the TGF-β/Smad3 pathway, which is inconsistent with our results." (PMID 39684261, 2024). "By using whole transcriptome RNA sequencing, we identified novel Smad3 transcripts related to the development of diabetic nephropathy." (PMID 33369170, 2021). "Overactivation of TGF-β1/Smad3 signaling is accompanied by the degradation of Smad7, contributing to the activation of NF-κB signaling in diabetic nephropathy." (PMID 34775979, 2021). "Mechanistically, BHD inhibited the activation of TGF-β1/Smad3 and NF-κB signaling in diabetic nephropathy while suppressing Arkadia expression and restoring renal Smad7." (PMID 34775979, 2021). "Astragalus, a monarch herb of BHD, was found to protect against diabetic nephropathy via suppressing TGF‐β/Smad3 signaling in diabetic mice." (PMID 34775979, 2021). "Under fibrosis conditions, Smad7 is reduced while Smad3 is highly activated as seen in diabetic nephropathy, hypertensive nephropathy, and aristolochic acid-induced nephropathy." (PMID 32258028, 2020). "In conclusion, the ATRQβ-001 vaccine ameliorated streptozotocin-induced diabetic renal injury via modulating two RAS axes and inhibiting TGF-β1/Smad3 signal pathway, providing a novel, safe, and promising method to treat diabetic nephropathy." (PMID 26407577, 2016). "TXL reduced the expression of ECM proteins and interfered with SMAD3 signaling, similar to its effects in the kidneys of rats with diabetic nephropathy." (PMID 26673167, 2015). "FFA induces the over-expression of TGFBRII as noted in diabetic kidney disease and it increases the expressions of proto-oncogenes and SMAD3 in TGFB signalling process." (PMID 19997558, 2009). "QDPR may be an important factor in mediating diabetic nephropathy through regulating TGF- TGF 1/ Smad3 signaling and NADPH oxidase." (PMID 35320116, 2022). "Suppression of SMAD3 activity was shown to depress fibrosis, apoptosis, and inflammation in mouse kidneys with unilateral ureteral obstruction and inhibited the development of diabetic nephropathy in a mouse model of type 1 diabetes." (PMID 35085106, 2022). "Thus, therapeutic strategies can be based on targeting the TGF-β1/Smad3 and NF-κB/p65 pathways to attenuate the progress of diabetic nephropathy." (PMID 34775979, 2021).
diabetic nephropathy (continued). "Thus, suppression of TGF-β1/Smad3 signaling represents a critical therapeutic approach to reduce renal inflammation and fibrosis in diabetic nephropathy." (PMID 34775979, 2021). "Notably, Smad7 is a key protein to suppress the activation of TGF‐β/Smad3 and NF-κB signaling pathways in diabetic nephropathy." (PMID 34775979, 2021). "Thus, we tested the effects of BHD on the TGF-β1/Smad3 signaling pathway in the mice model of diabetic nephropathy." (PMID 34775979, 2021). "In the study, we tested the hypothesis that BHD could attenuate renal inflammation and fibrosis in diabetic nephropathy, and its underlying mechanisms would be related to inhibiting the TGF-β1/Smad3 pathway." (PMID 34775979, 2021). "In addition, SIS3, a selective compound that targets only Smad-3 delayed the progression of diabetic nephropathy in a mouse model by reducing the expression of ECM proteins." (PMID 29039786, 2017). "Similarly, genetic abrogation of TGF-β signaling by Smad3 knockout was found to be insufficient to prevent proteinuria in a streptozotocin (STZ)-induced diabetic nephropathy model, despite significant protection from glomerular hypertrophy and GBM thickening." (PMID 27187580, 2016). "Notably, TGF-β1/Smad3 signaling is involved in diabetic nephropathy." (PMID 34775979, 2021). "Thus, Smad3 may be essential in the pathogenesis of diabetic and hypertensive complications, which is validated by our recent finding that diabetic db/db mice null for Smad3 are resistant to the development of diabetic nephropathy." (PMID 33733577, 2021). "In diabetic nephropathy, where COL-IV is a major deposited collagen, Smad3 binds to promoter regions of COL4A1A2, COL4A3A4, and COL4A5, a process inhibited by C-peptide." (PMID 40646747, 2025). "As part of the TGF-β1 pathway, SMAD proteins, particularly SMAD2, SMAD3, SMAD4, and SMAD7, are crucial in diabetic nephropathy." (PMID 38972889, 2024). "SMAD family member 3 (SMAD3) directly binds to the 3′‐UTR of Tfeb and inhibits its transcription, which triggers lysosome depletion in tubular epithelial cells in diabetic nephropathy." (PMID 36184826, 2023). "It prevented inflammation and fibrosis in diabetic nephropathy by inhibiting the NF-κB and TGF-β1/Smad3 signaling pathways." (PMID 34253875, 2022). "We logically investigated the effects of BHD on the TGF-β1/Smad3 and NF-κB/p65 signaling pathways in the STZ-induced diabetic nephropathy mice." (PMID 34775979, 2021). "In contrast, an inhibitory Smad, Smad7, represses TGF-β/Smad3 and NF-κB signaling pathway by interacting with TGF-β receptors and functions as an antagonist of these molecules in diabetic nephropathy." (PMID 34775979, 2021). "After diabetic nephropathy mice were treated with BHD (2 g/kg), the expressions of p-Smad3, Arkadia, p-p65 were significantly down-regulated whereas the expression of Smad7 was upregulated." (PMID 34775979, 2021). "Smad2 and Smad3 are activated in kidneys of patients with CKD and experimental animals of unilateral ureteral obstruction (UUO), 5/6 nephrectomy, hypertensive nephropathy and diabetic nephropathy." (PMID 32957963, 2020). "The authors showed that administration of a selective Smad3 inhibitor (SIS3), to both in vitro cultured mouse pancreatic microvascular endothelial cells and in Tie-2-EGFP mice where diabetic nephropathy was induced by STZ, resulted in reduced EndMT and fibrosis." (PMID 29039786, 2017). "Therefore, we speculate that BHD may protect against diabetic nephropathy probably by suppressing the Arkadia-dependent ubiquitin degradation of renal Smad7 and TGF-β/Smad3 signaling pathways." (PMID 34775979, 2021). "Previous studies have reported that miR-330-5p may be involved in the synaptic loss of hippocampal neuron during Alzheimer's disease pathogenesis; miR-346 negatively regulates Smad3/4 expression by binding to its 3'-UTR, ameliorating the kidney function and histology in diabetic nephropathy." (PMID 30118515, 2018).
diabetic nephropathy (continued). "Targeting LRNA9884 effectively blocks MCP-1-dependent renal inflammation, and Smad3 interactions or Smad3-dependent interactions between LRNA9884 and MCP-1 may be an additional mechanism by which Smad3 deletion in db/db mice suppresses renal inflammation in diabetic nephropathy." (PMID 34712322, 2021). "Thus, we tested the hypothesis that the anti-fibrotic and anti-inflammatory effects of BHD might be attributed to blocking the Smad3 phosphorylation and Arkadia, subsequently increasing renal Smad7 and inhibiting NF-κB signaling in the STZ-induced diabetic nephropathy mice." (PMID 34775979, 2021).
colon carcinoma (50 papers, 2007 to 2025). "For example, Smad2 and Smad3 mutations have been found in colon cancer, pancreatic cancer, and other tumors." (PMID 34489426, 2021). "Pri-miR-21 is among the SMAD3 target pri-miRNAs and its level was previously associated to tumor response to 5-FU-based treatment in patients affected by colon cancer." (PMID 26934318, 2016). "Meeker and his colleagues found that dietary vitamin D supplementation had a preventive effect on inflammation-associated colon cancer by lowering inflammatory cytokines induced in response to Hb in Smad3-/- mice." (PMID 26790152, 2016). "Since Smad2 and Smad3 are rarely mutated in colon cancer, Smad2 phosphorylation was used in this study to indicate active TGF-beta/Smad2/3 signaling." (PMID 23536895, 2013). "We hypothesize that a deficiency in TGF-β signaling through loss of SMAD3, combined with the presence of Helicobacter hepaticus, alters microbial ecology, leading to functional dysbiosis and colon cancer." (PMID 28951889, 2017). "Interestingly, a mouse model deficient for Smad3 has been reported to spontaneously develop colon cancer, and Smad4 deficiency greatly exacerbates a mouse model of colon cancer." (PMID 23555575, 2013). "Zhu reported that Smad3-deficient mice develop colon carcinoma." (PMID 22539990, 2012). "Similarly, colon cancer in SMAD-3-deficient mice is enhanced by dual infection with H. hepaticus and H. bilis." (PMID 19034278, 2009). "Indeed, human colon carcinoma cell lines of known Ras activating mutations show a correlation between the oncogenic Ras and a deficient nuclear accumulation of activated Smad2 and Smad3." (PMID 29534718, 2018). "Next, we confirmed the expression of RAD51C, RFC4, SIRT1, SIRT5, and SMAD3 genes in different colon cancer cell lines." (PMID 39110260, 2024). "Conversely, SIRT1 and SMAD3 displayed high differential expression in LEV-treated Caco-2 cells while showing low differential expression in TCGA colon cancer tissue samples." (PMID 39110260, 2024). "Among six nuclear receptors examined, only Nur77 significantly enhanced TGFβ-induced CAGA reporter activity in both HEK293T kidney and HCT116 colon cancer cells, indicating the positive role of Nur77 in TGFβ/Smad3 signaling." (PMID 33990575, 2021). "In summary, we provided evidence that lncRNA MIR570MG augmented in regorafenib-resistant colon cancer cells and conferred resistance by sponging with miR-145, leading to the promotion of Smad3-mediated cell survival, colony formation, and tumor growth." (PMID 32195190, 2020). "The phosphorylation of Smad3 was maximally increased 120 min after TGF-β1 stimulation in the colon cancer cell line HT-29." (PMID 31484999, 2019). "We examined the human colon cancer cell line HT-29, which showed the phosphorylation of Smad3 after TGF-β1 stimulation." (PMID 31484999, 2019). "The SMAD7, SMAD3, BMP2, and C-MYC regions were associated with colon cancer; however, after BH correction, only SMAD7 (PBH = 0.04) and SMAD3 (PBH = 0.009) remained statistically significant." (PMID 31434255, 2019). "Even though both SMAD3 deficiency and H. hepaticus inoculation are required for colon cancer in this model, the OXPHOS pathway is changed more by H. hepaticus than by SMAD3 deficiency." (PMID 28951889, 2017). "Our results suggest that the actions of TrkC are positioned upstream of Smad2 and Smad3 phosphorylation; therefore, we examined the possibility that TrkC directly interacts with TβRII in normal colon cells and colon cancer cells." (PMID 28455963, 2017). "In both the Tgfb1−/−Rag2−/− and Smad3−/− models, colon cancer develops only in conjunction with the presence of gut microbial Helicobacter species." (PMID 28951889, 2017). "Lithium reduces the expression of transforming growth factor-β-induced protein (TGFBIp) in colon cancer cells by inhibiting Smad3 phosphorylation via GSK3β inactivation." (PMID 26857144, 2016).
colon carcinoma (continued). "GSK3B and SMAD3 are proteins involved in the KEGG colon cancer pathway and the remaining three are first-degree neighbors." (PMID 24886433, 2014). "Reduced exposure of Smad3−/− mice to DSS allowed animals to survive the acute phase of disease and was associated with development of colon cancer at later time points." (PMID 24244446, 2013). "Previous studies have shown a requirement for a bacterial trigger for the colitis and colon cancer phenotype in Smad3−/− mice." (PMID 24244446, 2013). "The propensity toward colon cancer development in Smad3−/− animals is likely attributable to many abnormalities." (PMID 24244446, 2013). "Taken together with the observation that PKA activation is Smad3-dependent, these results indicate that TGF-beta/Smad3/PKA signaling regulates downregulation of VEGFA expression in colon cancer cells." (PMID 23536895, 2013). "We therefore were surprised to find that >80% of Smad3+/−; Rab25−/− mice demonstrated large invasive colon tumours throughout the colon by 15 weeks of age." (PMID 21063400, 2011). "It is perhaps not surprising that combining these two transcriptional programs results in increased number and invasiveness of colonic tumors as recently reported for ApcMin/+ mice crossed to Smad3-/- mice." (PMID 17615082, 2007). "We further investigated the role of CEACAM1 in ammonia-mediated disruption of TGF-β signaling, by examining p-SMAD3 in SW480 human colon cancer cells after overexpressing either full-length CEACAM1 (CEACAM1-FL) or a C-terminal deletion mutant lacking the ITIM motif (CEACAM1-ΔC)." (PMID 40311681, 2025). "Squamous cell lesions of unknown origin have been observed in colonic polyps of CDX2-knockout mice, and likewise in SMAD3-depleted and SMAD3-knockout colonic tumors given DSS compared to DSS alone." (PMID 35600339, 2022). "Additionally, rAF-IL12 was shown to also increase the expression level of Smad3, which is known to be involved in inhibiting survival, proliferation, and tumorigenesis in colon cancer in response to transforming growth factor-β (TGF-β) stimulation." (PMID 33354412, 2020). "We further investigated alternative mechanisms underlying FoxO3 modulation and asked whether the Akt/FoxO3 and myostatin/Smad3 axis were affected by implanted C26 colon carcinoma cells and JQ1 administration." (PMID 29167426, 2017). "In genetic mouse models, Smad3 or Smad4 mutation increases malignancy and invasiveness of intestinal tumors in APC min/+ or APC Δ716/+ mice, pointing to a significant role of TGFβ signaling in repressing malignant progression in colon tumors." (PMID 28414818, 2017). "Further studies are needed to investigate whether TGFβ/Smad3 regulates Cbl-b expression and/or activity in colon cancer cells and whether Cbl-b is responsible for suppression of IRS-1 expression by TGFβ/Smad3 signaling." (PMID 28414818, 2017). "Interestingly, our results show a significant downregulation of TGFBIp expression in colon cancer cells following lithium treatment, and further demonstrate that lithium induces this effect by inhibiting Smad3 phosphorylation though GSK3β inactivation." (PMID 26857144, 2016). "Fifteen genes (DUSP2, INFGR1, IL6, IRF2, JAK2, MAP3K10, MMP1, NFkB1A, NOS2A, PIK3CA, SEPX1, SMAD3, TLR2, TYK2, and VDR) were associated with colon cancer mortality (PARTP <0.05); JAK2 (PARTP = 0.0086), PIK3CA (PARTP = 0.0098), and SMAD3 (PARTP = 0.0059) had the strongest associations." (PMID 25541970, 2014). "Fifteen genes (DUSP2, INFGR1, IL6, IRF2, JAK2, MAP3K10, MMP1, NFkB1A, NOS2A, PIK3CA, SEPX1, SMAD3, TLR2, TYK2, and VDR) were significantly associated with colon cancer mortality at the <0.05 level; an additional 15 genes had gene PARTP values between 0.05 and 0.10." (PMID 25541970, 2014). "Interestingly, we found that Nodal promotes spheroid formation of CCSCs via the activation of Smad2 and Smad3 pathways, suggesting that Nodal is involved in self-renewal of colon cancer stem cells." (PMID 24696849, 2014).